CRP (C-reactive protein)
Diseases named in the same sentence as CRP in open-access papers (continued):
Sharing a sentence is not in itself a finding about the gene and the disease.
malaria (continued). "The present study indicates that CRP measurement in a routine laboratory could help clinicians in highly malaria-endemic areas to recognize malaria infection and determine its severity in patients." (PMID 34764364, 2021). "The goal of this study is to demonstrate the potential of a three-part differential hematology analyzer to assess malaria, provide information about the parasitemia, and discuss the importance of combining CRP with hematology parameters to obtain further information about the malaria infection." (PMID 34565334, 2021). "In Africa, where malaria is endemic, CRP was reported to aid the diagnosis of neonatal sepsis." (PMID 34764364, 2021). "Using CRP in combination with other routine laboratory parameters could serve as a biomarker for the early detection and monitoring of malaria severity." (PMID 34764364, 2021). "VAD and reported malaria in Chamwino and CRP/AGP in Kilosa predicted ID." (PMID 34066852, 2021). "However, there was a higher mean CRP level in patients with severe malaria than in those with uncomplicated malaria as estimated by the fixed-effects model (p < 0.001, SMD: 0.59, 95% CI: 0.47–0.70, 16 studies)." (PMID 34764364, 2021). "Ferritin levels are elevated for a prolonged period after a malaria infection, even after CRP levels have normalized, so that children with low ferritin levels may be less likely to have had recent malaria and thus might have reduced antibody levels." (PMID 32507899, 2021). "Interestingly, CRP is also elevated in malaria where erythrocytes can be lysed through antibodies targeting parasite antigens displayed on infected cells and/or phosphatidylserine on uninfected cells." (PMID 33790888, 2021). "Therefore, the potential usefulness of CRP includes ruling out other febrile illnesses in areas where malaria is endemic such as in sub-Saharan Africa." (PMID 34764364, 2021). "A combination of increased CRP level and other routine laboratory parameters might improve the ability of CRP to differentiate between severe and uncomplicated malaria." (PMID 34764364, 2021). "Moreover, the NLR was found to be correlated with malaria parasitemia, and it was inferior to CRP as a marker for severe imported malaria." (PMID 32574170, 2020). "Histidine-rich protein-2 (HRP-2), lactate, C-reactive protein (CRP) and procalcitonin (PCT), have all shown to be associated with poor outcomes in patients with SM, and have been considered for risk-stratification of children with malaria." (PMID 32709257, 2020). "Correlations were visualized with scatter plots of malaria-specific antibodies against VL and CRP." (PMID 31470903, 2019). "Elevated levels of IL‐1β lead to inflammatory events such as fever, increased circulating neutrophils, upregulation of surface markers in cells, extensive nitric oxide production, and elevated levels of CRP and inflammatory cytokines, which are all common in malaria." (PMID 31265218, 2019). "Despite the reported usefulness of traditional CRP tests in malaria, a more sensitive approach could potentially enhance early detection and monitoring of malaria severity." (PMID 31089391, 2019). "Based on this finding, a normal CRP may be used in ruling out malaria in febrile children in a context where malaria microscopy and RDT may not be readily available." (PMID 30080904, 2018). "However, the positive predictive values of elevated CRP for parasitemia and malaria were only 52.8% and 31.7%, respectively." (PMID 30080904, 2018). "However, the adjustment of RBP for malaria, in addition to CRP and AGP, with the use of the RC approach results in minimal changes in the estimated prevalence of VAD in children compared with values when adjusting for CRP and AGP only." (PMID 28615251, 2017). "For example, levels of biomarkers such as CRP may be elevated in malaria cases, which could lead to overtreatment with antibiotics and under-treatment with anti-malarials." (PMID 28753985, 2017).
malaria (continued). "However, malaria adjustments alone resulted in lower adjustments to CRP and AGP, which were consistent with past studies." (PMID 28615259, 2017). "The addition of malaria to the multiple regression analysis dampened the ln-CRP and ln-AGP slopes." (PMID 28615251, 2017). "CRP concentrations increase markedly during acute inflammatory events notably acute bacterial infections and systemic protozoal infections such as malaria." (PMID 27386859, 2016). "A number of studies have reported a relationship between clinical malaria and CRP." (PMID 27386859, 2016). "There have been studies to determine whether C-reactive protein and procalcitonin are effective biomarkers in the African region with mixed results particularly in malaria endemic regions." (PMID 27045667, 2016). "Thus far, there have been few comparative assessments of procalcitonin and CRP in malaria endemic areas, and those available have focused on hospitalised patients." (PMID 26558692, 2015). "In addition, one of the two inflammation biomarkers measured (CRP) showed significantly higher level (P<0.001) among khat chewer malaria patients." (PMID 26173100, 2015). "Notwithstanding the need for further prospective studies of CRP guided treatment in these settings, these findings suggest that there may well be a role for CRP point of care tests in guiding antibiotic treatment of fevers in malaria endemic areas." (PMID 26558692, 2015). "C-reactive protein measurements at the time of malaria diagnosis showed higher acute inflammatory responses in naïve compared to semi-immune volunteers (57.7 mg/dL vs 17.6 mg/dL; p = 0.036), which appears to be associated with clinical findings in naïve volunteers." (PMID 24963662, 2014). "Owing to the high seasonality of malaria transmission in The Gambia and the fact that both CRP and Lpc-2 have been shown to increase in children with malaria, it is plausible that this increase in sensitivity and specificity is explained by the low number of malaria infections during the dry season." (PMID 24696240, 2014). "CRP is an acute-phase inflammatory protein, and this study findings indicate that participants homozygous (CC) for DDX39B-22 (G > C) had increased levels of CRP, supporting an association of the C allele with risk of complicated malaria." (PMID 25038626, 2014). "CRP serum levels above or below 10.8 mg/l upon hospital admission, in combination with travel history to an endemic area, and fever during the days prior to blood sampling, best discriminated between malaria patients and control subjects." (PMID 23866258, 2013). "Moreover, CRP has already been used as a biomarker of malaria in febrile patients returning from tropical areas and in epidemiological investigations in endemic areas." (PMID 24069477, 2013). "Nevertheless, in this study, the CRP did not allow to differentiate malaria from other causes of fever in travelers." (PMID 24069477, 2013). "Repartition of the dengue and malaria patients depending on the C-reactive protein (CRP) level." (PMID 24069477, 2013). "The rising availability of rapid tests for dengue and malaria may diminish the interest of CRP to differentiate these two major diseases." (PMID 24069477, 2013). "Using a recessive model the FcγRIIA R allele, which has higher binding to CRP and lower binding to IgG, was positively associated with severe malaria, but not with cerebral malaria." (PMID 24167754, 2013). "The A-allele, unlike the C- and T-alleles or CRP genotypes, was significantly associated with an increased number of malaria episodes, P = 0.007 and increased parasite counts." (PMID 24167754, 2013). "In addition to high Hpr levels, CRP levels were also high in Gabonese children, greater than 80% of whom were defined as having an APR (CRP>10 μg/ml) related to malaria parasitemia." (PMID 23185445, 2012). "However, the usefulness of CRP for the prediction of severe malaria in clinical practice is probably limited." (PMID 22221299, 2012).
malaria (continued). "A significant correlation was demonstrated between sodium levels and CRP levels on admission for all patients with imported malaria (n = 428; rs = -0.36; p < 0.0001) but also for patients with infections solely caused by Plasmodium falciparum (n = 298; rs = -0.41; p < 0.0001)." (PMID 20497587, 2010). "Increased C reactive protein (CRP) is an indicator of inflammation and is associated with malaria." (PMID 21144084, 2010). "Further research on the effect of CRP on malaria susceptibility is warranted, since recent studies on new therapeutic agents, that lower the circulating CRP levels, might open up new adjunct treatment options against malaria." (PMID 19545442, 2009). "The results of the present study may suggest, that a high level of circulating CRP can be detrimental for malaria protection, although by a yet unknown mechanism." (PMID 19545442, 2009). "An optimal cut-off value of CRP based on malaria transmission intensity (moderate transmission in our population, cut off > 40 mg/L), its integration into duo RDT, and the utility of these tests to change clinical practice may be instrumental to reducing the indiscriminate use of antibiotics." (PMID 39177882, 2025). "Additionally, increased CRP has been used as a biomarker of malaria severity." (PMID 39066199, 2024). "However, we found difficulties for the specific RDTs used in this study, the most prominent being sample collection for the larger quantity of blood (Dengue Duo), the complexity of the test procedure (Malaria/CRP Duo) and the quantitative result interpretation (DPP Fever Panel Asia II)." (PMID 37317948, 2023). "Several factors might contribute to changes in C-reactive protein levels in patients with malaria." (PMID 37771844, 2023). "Some biomarkers (C-reactive protein, angiopoietin 2, angiopoietin-2/1 ratio, platelet count, histidine-rich protein 2) have yielded interesting results in the prognosis of Plasmodium falciparum severe malaria, but for severe P. vivax and P. knowlesi malaria, similar evidence is missing." (PMID 36036460, 2022). "However, the setting is non‐endemic for malaria, and the presence of common infection and/or inflammation as measured by the CRP > 5 mg/L was 4.9% (school children) and 9.5% in non‐pregnant non‐lactating women which is an acceptable level for a developing country." (PMID 35383403, 2022). "Therefore, CRP measurement may be useful for the physician to follow-up on the efficacy of treatment of malaria." (PMID 34764364, 2021). "Since CRP levels correlate with disease severity, CRP may also directly participate in exacerbation of antibody-mediated erythrocyte destruction next to its demonstrated functional involvement in complement-mediated erythrocyte destruction in malaria." (PMID 33790888, 2021). "In addition, a CRP level greater than 5 mg/L could discriminate malaria from dengue infection with a sensitivity of 95% but with a poor specificity of 35%59." (PMID 34764364, 2021). "Besides the usefulness of CRP as an early marker for malarial infection and severity, it could be used as a prognostic marker for the efficacy of malaria treatment as CRP level was reported to be decreased under malaria treatment." (PMID 34764364, 2021). "The current study suggests that CRP could be helpful for distinguishing malaria from dengue." (PMID 34565334, 2021). "In addition, elevated levels of CRP, an acute phase inflammatory protein, were consistently observed in febrile malaria-positive individuals, in contrast to asymptomatic malaria-positive individuals, supporting the correlation of the CRP level with complications in malaria." (PMID 32189616, 2020). "Similarly, CRP levels had a limited ability to identify malaria in the study presented here." (PMID 30080904, 2018). "This association could reflect an added influence of malaria-related inflammation on temporary reductions in RBP concentrations that is not captured by CRP and AGP." (PMID 28615251, 2017).
malaria (continued). "Alternatively, or in addition, it may be the effect of residual confounding of malaria-associated inflammation that are not fully captured by CRP or AGP." (PMID 28615259, 2017). "Treatment algorithms based on CRP and malaria RDTs have the potential to guide the rational use of antibiotic treatment, but if plasma CRP concentrations in these populations are commonly elevated for other reasons this could undermine the utility of such an approach." (PMID 27386859, 2016). "Inflammatory factors, other than hepcidin, may inhibit erythroblast iron incorporation as this was not correlated with hepcidin, malaria, or IL-6, but was significantly associated with raised CRP values." (PMID 24339866, 2013). "CRP levels were measured with a high sensitivity assay in 624 apparently healthy individuals who contributed blood as part of a study on innate immune responsiveness in a traditional Ghanaian population living under adverse environmental conditions in a malaria endemic area." (PMID 23922912, 2013). "Finally, in case of positive dengue RDT, an elevated CRP level may hint at looking for malaria or bacterial co-infection." (PMID 24069477, 2013). "Although the exact trigger for inappropriate AVP release remains unknown, the higher body temperatures, correlations with C-reactive protein and long normalization times of serum sodium, suggest an important role of the host inflammatory response to the invading malaria parasite." (PMID 22280539, 2012). "C-reactive protein remained unaffected by Plasmodium falciparum parasitemia, while procalcitonin (PCT) was more frequently detectable among malaria-positive individuals." (PMID 41799261, 2026). "Malaria/CRP RDT testing resulted in 48 out of 1,510 (3.2%) patients testing CRP-positive (> 20 mg/L), and three P. falciparum-positive results being recorded on the eCRF." (PMID 40340660, 2025). "Blood samples were taken off to do laboratory measurements that included: HIV serostatus, C-reactive protein (CRP), white blood cell count and a blood smear for malaria parasites." (PMID 41026768, 2025). "During malaria, tissue damage and immunological activation result in the release of inflammatory cytokines, which in turn boost the liver’s production of AGP and CRP, and their levels increase in blood during parasitic infections." (PMID 40277833, 2025). "In the Malawi (iLiNS-DYAD) cohort, we examined correlations between maternal Cu concentration and common analytes including APRs (CRP, AGP, and ALB) and infections (HIV and malaria) in 1239 samples collected at enrollment." (PMID 37890672, 2024). "Studies have recently shown that a C-reactive protein (CRP) > 50 mg/l is highly suggestive of a diagnosis other than dengue, such as leptospirosis or malaria." (PMID 37376570, 2023). "In the intervention arm, a malaria RDT was performed in 99% of patients overall, white blood cell (WBC) total and neutrophil counts in 96.9%, and C-reactive protein (CRP) in 96.6%; these values were consistent across the 3 countries." (PMID 37490743, 2023). "In the group suffering from malaria, creatinine averaged 0.98 mg/dL, bilirubin 0.78 mg/dL, LDH 246 U/L and CRP 8.4 mg/L." (PMID 36961624, 2023). "Furthermore, a study concluded that CRP > 35 mg/L was highly sensitive in predicting mortality in subjects with malaria, and another study demonstrated CRP may be a biomarker for the early detection and management of malaria severity." (PMID 37873776, 2023). "We included C-reactive protein, Influenza A and B, Group A streptococcus, Procalcitonin, Helicobacter pylori, Mononukleosis, Respiratory syncytial virus, HIV, Malaria, Chlamydia, Borreliosis, and Syphilis." (PMID 35264103, 2022). "The Q-PlexTM Human Malaria assay measured whole blood and plasma concentrations of HRP2, pan-LDH, Pf-LDH, Pv-LDH and CRP." (PMID 35508558, 2022). "Among participants assessed at enrollment, 61% were anemic, 35% had elevated CRP (>5 mg/L), 60% had elevated AGP (>1 mg/L), and 13% tested positive for malaria antigens." (PMID 35755939, 2022).
malaria (continued). "The markers forming the first cluster tended to increase the MDP values in the group of symptomatic malaria, with remarkable high values of TNF-α, IL-6, CXCL9, AST, CRP, IL-8 and ALT." (PMID 34727121, 2021). "In the LC-667G CRP HORIBA analyzer, an abnormal peak located approximately at the 37fL channel in the WBC histogram appears mainly in malaria P. vivax samples with high density of large forms of parasites." (PMID 34565334, 2021). "Comparing both malaria infected cases with dengue, only PLT, PCT and CRP medians had a significant difference, which makes it difficult to differentiate between both diseases when observing solely the hematology parameters affection." (PMID 34565334, 2021). "CRP, PCT, viral multiplex PCR on nasopharyngeal swabs and bacterial- and malaria PCR were batch-tested retrospectively." (PMID 33647009, 2021). "Raw data from the three-part analyzer LC-667G CRP (HORIBA) and the corresponding microscopic findings (golden standard for diagnosis of malaria) were obtained for each sample." (PMID 34565334, 2021). "Similar trends were seen among malaria specific antibody concentrations to AMA1 and GLURP-R0 with weak correlations of HIV-1 viral load and CRP with IgM and IgG1 concentration." (PMID 31470903, 2019). "The 2-plex array was recently expanded into a 4-plex array to include assays that quantify HRP2, pan LDH (all malaria), and P. vivax LDH and to monitor host inflammatory response via CRP." (PMID 30404944, 2019). "A new diagnostic tool that can quantify the two most commonly used antigens in malaria RDTs, HRP2 and pLDH, as well as the inflammation marker CRP, from the same blood sample was developed." (PMID 30404944, 2019). "At Visit 1, compared with uninfected women, malaria-infected women had significantly higher levels of CHI3L1, CRP, sICAM-1, IL-18BP, sTNFRII, and sEng and lower levels of Leptin (p ≤ 0.005)." (PMID 31574087, 2019). "Six representative examples, showing both increased (ADSSL1, CEBPA, CRP, LBP) and decreased protein levels (CCL5, SPARC) in malaria patients compared to controls are shown in." (PMID 30442134, 2018). "Out of the six proteins, three were identified as showing increased levels (CRP, CSF1, LBP) in malaria patients compared to controls while the remaining three displayed decreased levels (CCL5, CTSD, SPARC)." (PMID 30442134, 2018). "This study is meant as a step forward in comparing different approaches to accurately and feasibly assess the prevalence of VAD in populations for CRP and AGP and, when appropriate, malaria." (PMID 28615251, 2017). "There was no multicollinearity between ln CRP and ln AGP or between ln CRP, ln AGP, and malaria in the PSC and WRA models across surveys." (PMID 28615259, 2017). "Several approaches have been proposed about how to use CRP and AGP to account for inflammation and infections such as malaria to increase the sensitivity of detecting depleted iron stores at the population level." (PMID 28615259, 2017). "When CRP and AGP are measured, there appears to be limited utility in measuring malaria status to adjust ferritin concentrations." (PMID 28615259, 2017). "The findings from this large, multicountry analysis show that RBP concentrations were lower in individuals with elevated CRP and AGP concentrations and/or malaria than in individuals with low inflammation." (PMID 28615251, 2017). "The CFs were <1 across all group combinations (CRP, AGP, and malaria) and surveys for both PSC and WRA." (PMID 28615259, 2017). "However, when the data in the two study groups were pooled together and treated as one, the stepwise regression analyses showed that malaria-induced CRP level could be independently (R2 = 0.749 and adjusted R2 = 0.591; P = 0.026) predicted by baseline CRP level only." (PMID 27298824, 2016).